JAK2 (Janus kinase 2)
Diseases named in the same sentence as JAK2 in open-access papers (continued):
Sharing a sentence is not in itself a finding about the gene and the disease.
gout (5 papers, 2016 to 2025). A condition characterized by painful swelling of the joints, which is caused by deposition of urate crystals. "Additionally, the levels of IL-6 protein and JAK2 mRNA were positively correlated with certain inflammatory markers, reflecting their association with gout’s clinical and laboratory activities." (PMID 40170729, 2025). "During gout flare-ups, the JAK2/STAT3 signaling pathway is activated, leading to increased expression of cytokines such as IL-6, IL-1β, and TNF-α in both the kidneys and joints." (PMID 39611154, 2024). "During gout flare-ups, the activation of JAK2/STAT3 signaling results in an elevation of cytokine expression, including IL-6, IL-1β, and TNF-α, within the kidneys and joints." (PMID 38094893, 2023). "Lagotis brachystachya Maxim., primarily employed for treating yellow water disease (gouty arthritis) and hepatitis, is capable of reducing the expression of phospho-JAK2 and phospho-STAT3." (PMID 38094893, 2023). "Furthermore, Compared to 12-hour gout model WT mice, IL-1β, IL-6, JAK2, STAT1/3 mRNA, protein expression, and phosphorylated protein levels were notably decreased in IL-6 KO mice." (PMID 40170729, 2025). "Therefore, in the present study, the underlying protective role and mechanism of ELB involved in TLR4/NF-κB, NLRP3, and JAK2/STAT3 inflammatory signaling pathways were investigated in chronic alcoholic liver injury combined with gouty arthritis." (PMID 36176434, 2022). "Furthermore, the 2-h human blood ex vivo gout inflammation model showed significantly elevated levels of IL-1β, IL-6, JAK2 mRNA, and their respective proteins, including phosphorylated JAK2 and STAT1/3, compared to both control groups." (PMID 40170729, 2025). "In GA patients, mRNA expression of IL-6, JAK2, STAT1/3, and IL-1β was notably lower in the gout group compared to the healthy control (HC) group." (PMID 40170729, 2025). "The expression levels of IL-1β, IL-6, JAK2, and STAT1/3 mRNA were significantly lower in the gout group compared to the HC group (all P < 0.001)." (PMID 40170729, 2025). "In the 6-h acute gout cell model, expression levels of IL-1β, IL-6, JAK2, STAT1/3 mRNA, and their respective proteins—including phosphorylated JAK2 and STAT1/3—were significantly elevated in the model group compared to the blank control group." (PMID 40170729, 2025). "In the 2h human blood in vitro gout inflammation model, expressions of IL-1β, IL-6, JAK2 mRNA, and IL-1β, IL-6, JAK2, STAT1/3, p-JAK2, p-STAT1/3 proteins were significantly higher compared to both the blank control and PBS-negative control groups." (PMID 40170729, 2025). "Moreover, IL-6, JAK2, STAT1/3, p-JAK2, p-STAT1/3, and IL-1β proteins were markedly higher in the acute gout (AG) group compared to the intercritical gout (IG) and HC groups." (PMID 40170729, 2025). "For example, targeting the JAK2/STAT3 signaling pathway could reduce the expression of pro-inflammatory cytokines like IL-6, IL-1β, and TNF-α, thereby alleviating gout symptoms and slowing disease progression." (PMID 39611154, 2024).
hyperlipidemia (5 papers, 2020 to 2023). "A widely used drug, ruxolitinib, is a JAK2/STAT3 inhibitor that causes hyperlipidemia and increases the body mass index." (PMID 36830925, 2023). "The leptin/Janus kinase 2 (JAK2)/signal transducer and activator of transcription 3 (STAT3) pathway is significantly associated with the pathogenesis of hyperlipidemia via alterations in lipid metabolites." (PMID 36539694, 2022). "leaf (COE) in hyperlipidemia via the leptin/Janus kinase 2 (JAK2)/signal transducer and activator of transcription 3 (STAT3) pathway." (PMID 36539694, 2022). "Leptin may contribute to hyperlipidemia through the OB-R-mediated activation of the JAK2/STAT3 pathway, which affects lipid metabolism and fat deposition in hepatic tissue." (PMID 36539694, 2022). "Thus, we propose that the leptin/JAK2/STAT3 pathway may be the regulatory target of COE in hyperlipidemia treatment." (PMID 36539694, 2022). "Thus, quercetin may mediate the role of COE in the leptin/OB-Rb/JAK2/STAT3 pathway in a rat model of hyperlipidemia." (PMID 36539694, 2022). "COE activates the leptin/JAK2/STAT3 pathway, leading to an improvement in liver function and lipid metabolism and ultimately alleviating hyperlipidemia in rats." (PMID 36539694, 2022). "That is, SOCS3, as a classic negative regulator of JAK2/STAT3, was up-regulated with the progression of inflammation aggravated by hyperlipidemia." (PMID 32169038, 2020).
idiopathic pulmonary fibrosis (5 papers, 2018 to 2025). Idiopathic pulmonary fibrosis (IPF) is a nonneoplastic pulmonary disease that is characterized by the formation of scar tissue within the lungs in the absence of any known cause. "A single study using PCLS prepared from control subjects and patients with either idiopathic pulmonary fibrosis (IPF) or IPF and PH (IPF + PH) has implicated Janus kinase type 2 (JAK2) as a novel target to oppose contraction of intrapulmonary arteries." (PMID 37261291, 2023). "Recent studies in patients with idiopathic pulmonary fibrosis (IPF) and PH have also shown increased expression of JAK2 and STAT3 in pulmonary arteries." (PMID 39125996, 2024).
iron overload (5 papers, 2010 to 2025). "We therefore hypothesize that HH‐related iron overload is toxic for the JAK2 clone and hinders clinical manifestation of the PV phenotype." (PMID 35844679, 2021). "A study has confirmed that SDG prevents the oxidative stress-induced apoptosis by regulating the JAK2/STAT3 signaling pathway in myocardial cells and abrogates the observed increases in ROS and apoptosis in cardiac iron overload condition." (PMID 32684834, 2020).
keloid (5 papers, 2021 to 2025). An irregularly shaped, elevated mark on the skin caused by deposits of excessive amounts of collagen during wound healing. "Subsequent research identified over activity of signal transducer and activator of transcription 3 (STAT3; in conjunction with JAK2) as a central mediator of keloid pathology." (PMID 33662027, 2021). "Given that both STAT3 and JAK2 are functions are abnormal in keloid derived cells, we hypothesized that pharmacologic and mutational disruptions of JAK2/STAT3 would influence both the metabolic and proliferation/migration abnormalities seen in keloid cells." (PMID 33662027, 2021). "Recent research has noted that the JAK2 inhibitor AG490 hindered the JAK2/STAT3 pathway, which in turn inhibited the abnormal proliferation and fibrosis of keloid fibroblasts, suggesting a potential role for this pathway in the development of HS." (PMID 39132968, 2024). "Interestingly, both IL-6 and its second messengers, Janus kinase 2 (JAK2) and signal transducer and activator of transcription 3 (STAT3), are elevated in keloids." (PMID 39919369, 2025). "However, given that folate degradation is reduced in pigmented skin and induces JAK2/STAT3, we hypothesized that greater cutaneous folate levels may contribute to keloid pathogenesis." (PMID 33662027, 2021).
liver cirrhosis (5 papers, 2015 to 2023). "Patients with the mutation JAK2 p.V617F: site of thrombosis, previous thrombotic event, malignancy, and liver cirrhosis." (PMID 38274463, 2023). "JAK2 rs V617F mutation as a potential risk factor of PVT was studied added to other thrombophilic disorders in a cohort with liver cirrhosis and HCC." (PMID 33507708, 2021). "The distribution of JAK2 mutation among idiopathic PVT cases with either HCC or liver cirrhosis was about 28/100 (28%), while secondary causes (cases with other thrombophilic risk factors) were found to be 72/100 (72%)." (PMID 33507708, 2021). "role of JAK2 RS V617F mutation as a risk factor for PVT development in liver cirrhosis and HCC." (PMID 33507708, 2021). "We present the first case of BCS secondary to Janus tyrosine kinase 2 (JAK2) mutation resulting in "pseudocirrhosis" rather than cirrhosis of the liver." (PMID 32850227, 2020).
lung squamous cell carcinoma (5 papers, 2021 to 2025). "Overexpression of FLT3 but not JAK2 significantly increased glucose consumption and blocked the ability of pacritinib to inhibit glucose consumption in squamous cell lung cancer cells." (PMID 36697489, 2023).
metastatic melanoma (5 papers, 2012 to 2023). A melanoma that has spread from its primary site to another anatomic site. "Additionally, in metastatic melanoma Colo857 cells, MHC is absent due to a genomic deletion of JAK2." (PMID 25690042, 2015).
papillary thyroid cancer (5 papers, 2021 to 2025). "Studies showed that miR-630 may inhibit metastasis and EMT of papillary thyroid cancer via the inactivation of JAK2/STAT3 signaling pathway." (PMID 35813296, 2022). "JAK2/STAT3 pathway also played a key role in driving angiogenesis and inflammatory crosstalk in papillary thyroid cancer cells, but there were no reports on this signaling pathway in the pathogenesis of thyroid nodules at present." (PMID 39494342, 2024). "However, in papillary thyroid cancer, FTO acts as a tumor suppressor to inhibit APOE expression and hinder glycolysis via the IL-6/JAK2/STAT3 signaling pathway." (PMID 41184232, 2025).
primary polycythemia (5 papers, 2015 to 2023). "The region on chr1 includes RCL1, which has been associated with snout ratio and tail curl as well as JAK2, which contributes to human and canine primary polycythemia." (PMID 37582787, 2023). "Primary polycythemia is caused due to mutations in erythropoietin (EPO) receptor or Janus Kinase 2 (JAK2)." (PMID 36811053, 2023).
rheumatic diseases (5 papers, 2021 to 2025). "The three drugs that are routinely used and discussed in rheumatic diseases are tofacitinib (TOFA; works on JAK families in this order- JAK3 > JAK2 > JAK1), baricitinib (BARI; JAK1, JAK2, and TYK2), and upadacitinib (UPA; JAK1 > JAK2 and JAK3)." (PMID 40282506, 2025). "JAKi, with varying selectivity for JAK1, JAK2, JAK3, and Tyk2, have then the role of disrupting proinflammatory cytokine cascades in rheumatic diseases." (PMID 38554250, 2024).
small cell lung carcinoma (5 papers, 2009 to 2023). Small cell lung cancer (SCLC) is a highly aggressive malignant neoplasm, accounting for 10-15% of lung cancer cases, characterized byrapid growth, and early metastasis.
systemic mastocytosis (5 papers, 2015 to 2025). Systemic mastocytosis (SM) comprises a heterogeneous group of rare acquired and chronic hematological malignancies that are related to an abnormal proliferation of mast cells in tissue, including bone marrow, with or without skin involvement. "Other somatic gene alterations implicated in some cases of advanced systemic mastocytosis include mutations in TET2, SRSF2, ASXL1, RUNX1, CBL, JAK2, NRAS, and KRAS." (PMID 41440762, 2025). "Although the JAK2 V617F mutation has been frequently identified in BCR/ABL-negative MPN and is rarely present in other hematologic disorders, this mutation does occur in other hematologic malignancies, such as refractory anemia with ring sideroblast, AML and systemic mastocytosis." (PMID 25624900, 2015). "Of interest, this data contrasts with our recent report on JAK2 V617F and KIT D816V in patients with concurrent diagnosis of a MPN and systemic mastocytosis." (PMID 40681596, 2025). "Interestingly, NGS analysis did not detect any mutations in all the other KIT exons analyzed nor in other genes previously reported in patients with advanced systemic mastocytosis (TET2, SRSF2, ASXL1, RUNX1, CBL, JAK2, NRAS, and KRAS)." (PMID 41440762, 2025).
thalassemia (5 papers, 2009 to 2025). An inherited blood disorder characterized by a decreased synthesis of one of the polypeptide chains that form hemoglobin. "In addition, based on preliminary studies in animal models of thalassemia, it has been suggested that use of Jak2 and analogous of hepcidin peptide might have a role in limiting ineffective erythropoiesis and increased iron absorption." (PMID 21415988, 2009).
VEXAS syndrome (5 papers, 2023 to 2026). An adult-onset inflammatory disease that affects only males and is caused by somatic, not germline, mutations. "Thromboembolic events are common in JAK2-mutated MPN and are shown to also be common in VEXAS syndrome." (PMID 36879894, 2023). "Furthermore, anakinra, an inhibitor of IL-1/IL-1R1 signaling, and ruxolitinib, an inhibitor of JAK2 signaling, have been reported to treat VEXAS syndrome." (PMID 40906528, 2025). "Pacritinib, an oral inhibitor of IRAK1, JAK2, and ACVR1, has emerged as a promising therapeutic option for VEXAS syndrome." (PMID 41753113, 2026).
anaplastic large cell lymphoma (4 papers, 2019 to 2022). Anaplastic large cell lymphoma (ALCL) is a rare and aggressive peripheral T-cell non-Hodgkin lymphoma, belonging to the group of CD30-positive lymphoproliferative disorders, which affects lymph nodes and extranodal sites. "Interestingly, by genetic profiling of breast implant associated anaplastic large cell lymphoma (BIA-ALCL), JAK2 was found to fuse with its downstream node STAT3, and this is also the first reported fusion fact in BIA-ALCL." (PMID 34680295, 2021). "The genetic alteration of the chromosome 9p24.1 locus, the location of PD-L1, PD-L2, and JAK2 are the main mechanisms leading to PD-L1 and PD-L2 overexpression and are frequently observed in these CD30+ large cell lymphomas." (PMID 35884893, 2022). "As an exception, STAT1 was shown to be an oncogenic driver in T-cell acute lymphoblastic leukemia (T-ALL) and ALK+ anaplastic large cell lymphoma (ALCL), and STAT1 is associated with the JAK2 exon 12 mutation in the progression of myeloproliferative neoplasms (MPNs)." (PMID 31817042, 2019).
aortic aneurysm (4 papers, 2022 to 2025). A ruptured aneurysm located in the wall of the proximal portion of the descending aorta proceeding from the arch of the aorta. "The underlying mechanism possibly involves JAK2 V617-positive circulating leukocytes that demonstrate upregulation of genes associated with aortic aneurysm formation, including matrix metalloproteinase 9 (MMP-9)." (PMID 40135024, 2025). "Follow-up functional study on transgenic (JAK2V617F) mice further demonstrated a crucial role of hematopoietic JAK2 V617F in the development of aortic aneurysms." (PMID 39062663, 2024). "The JAK2/STAT3 pathway is involved in various biological processes, including inflammation and tissue damage and repair, and is critical in the formation and development of AD and aortic aneurysm." (PMID 40278823, 2025). "We also found that high doses of EPO induced dissecting aortic aneurysm in immunocompetent C57BL/6 mice, supporting the critical role of the JAK2 pathway in aortic disease, but we did not specifically investigated which cell type was activated in response to EPO supplementation." (PMID 36329047, 2022).
brain injury (4 papers, 2019 to 2024). Acute and chronic (see also brain INJURIES, CHRONIC) injuries to the brain, including the cerebral hemispheres, CEREBELLUM, and brain STEM. "In this study, we revealed that controlled reoxygenation treatment could reduce neuron and glial cell apoptosis caused by hypoxia and exert an anti-inflammation effect on hypoxia-induced brain injury mice by downregulating JAK2/STAT3 and AMPK/mTOR signaling pathway." (PMID 31719034, 2019). "For instance, it has been reported that JAK2 and STAT3 inhibitors can block an increase in pro‐inflammatory protein levels following ischemic brain injury." (PMID 36627822, 2023). "On the other hand, ICV injection of S1P into mice reduces food intake via JAK2/STAT3 dependent signaling, signaling molecules being also involved in leptin action and may act neuroprotective in brain injury." (PMID 33946318, 2021).
dermatomyositis (4 papers, 2023 to 2025). Dermatomyositis (DM) is a type of idiopathic inflammatory myopathy characterized by evocative skin lesions and symmetrical proximal muscle weakness. "Up to now, scholars only reported somatic variances of JAK2 and TIF1g (TRIM33) that may possibly correlate with dermatomyositis, but most of the studies were case reports or from malignancy-associated dermatomyositis." (PMID 40599779, 2025).
epilepsy (4 papers, 2021 to 2023). A brain disorder characterized by episodes of abnormally increased neuronal discharge resulting in transient episodes of sensory or motor neurological dysfunction, or psychic dysfunction. "In rats with experimental epilepsy, EPO protected myocardial cells from apoptosis via the JAK2/STAT5 pathway, and the inhibition of JAK2/STAT5 signalization by AG490 reduced the antiapoptotic effects of EPO." (PMID 34281163, 2021). "As detailed here, the activated CD8 T cells had the strongest positive correlation with PRKCQ and a negative correlation with JAK2, which indicates that expression levels of PRKCQ and JAK2 in epilepsy play an important role in activated CD8 T cell infiltration." (PMID 36138892, 2022).
gastric tumor (4 papers, 2014 to 2025). "A previous study identified the JAK2/STAT3 signal as a key driver of macrophage activation in gastric tumors." (PMID 39974738, 2025). "In addition, application of intraperitoneal WP1066 for 2 weeks, reduced gastric tumour volume by 50% in the gp130757FF mouse coincident with reduced JAK2 and STAT3 activation compared with vehicle-treated, littermate controls." (PMID 24804649, 2014).
Glucose intolerance (4 papers, 2011 to 2023). Glucose intolerance (GI) can be defined as dysglycemia that comprises both prediabetes and diabetes. "Its deletion provokes metabolic disorders in SH2B1 KO mice, including leptin resistance, obesity, and glucose intolerance whereas restoration of SH2B1 corrected these metabolic disturbances and improved JAK2-mediated leptin signaling and regulation of hypothalamic orexigenic neuropeptides." (PMID 36674935, 2023).
Hepatitis (4 papers, 2020 to 2025). Inflammation of the liver. "Our findings underscore the critical role of ROS-dependent Jak2/Stat3 pathway activation in the occurrence of HBV-induced liver inflammation, providing new insights into the pathogenesis of chronic hepatitis B." (PMID 42290660, 2025). "Furthermore, hypoxia‐induced activation of JAK2/STAT3 was inhibited by salidroside treatment, which is possibly a potential mechanism to ameliorate hypoxia‐induced liver inflammation." (PMID 34532015, 2021).
hepatoblastoma (4 papers, 2022 to 2026). Hepatoblastoma (HB) is a malignant hepatic tumor and is the most common pediatric liver cancer. "In conclusion, our study reports for the first time the significance of the SOCS2/JAK2/STAT5 axis in hepatoblastoma metastasis." (PMID 38071211, 2023). "Our study found that SOCS2 inhibits the migration and invasion of hepatoblastoma cells by inhibiting the JAK2/STAT5 signaling pathway." (PMID 38071211, 2023). "Meanwhile, the LNCRNA TUG1 was increased in hepatoblastoma, stimulating the downstream signaling pathway of JAK2/STAT3 and promoting angiogenesis in hepatoblastoma cells." (PMID 36104680, 2022). "Targeting JAK2/STAT5 signaling pathway might serve as a potential therapy strategy for metastatic hepatoblastoma." (PMID 38071211, 2023).
hereditary thrombophilia (4 papers, 2023 to 2025). "Another recent meta-analysis was performed on the prevalence of acquired and hereditary thrombophilia among Indian patients with non-cirrhotic PVT, thus showing PC deficiency in 10.7%, Janus kinase 2 (JAK-2) mutation in 8.5%, and antiphospholipid antibodies (APLA) in 7.5%." (PMID 38592411, 2024).